APOE (apolipoprotein E)
Diseases named in the same sentence as APOE in open-access papers (continued):
Sharing a sentence is not in itself a finding about the gene and the disease.
atherosclerosis (continued). "In the context of the present study, our findings that augmented TSP-1 expression in the vessel wall associates with robust atherosclerotic lesions displaying increased SMC content in MetS KKAy+/–ApoE–/– mice underscore a TSP-1-dependent mechanism underlying MetS-induced atherosclerosis." (PMID 36505365, 2022). "It has long been known that cholesterol and lipid metabolism play a critical role in the development of AD, as seen with the APOE4 isoform of APOE, which increases plasma low-density lipoprotein levels (thereby also increasing risk of atherosclerosis), while also increasing the risk for AD." (PMID 35872901, 2022). "ApoE-deficient (ApoE−/−) mice are commonly used to study mechanisms of atherosclerosis." (PMID 35735797, 2022). "ApoE deficient mice show severe hypercholesterolemia and develop atherosclerosis in a short time." (PMID 36009040, 2022). "Loss of manganese superoxide dismutase activity in ApoE−/− mice promotes atherosclerosis." (PMID 36497101, 2022). "Interestingly, in an atherosclerosis-prone apolipoprotein E-deficient (apoE−/−) mouse model, 10 mg/kg of Uro B displayed protective and healing effects against atherosclerosis." (PMID 35814202, 2022). "Metabolites derived from gut microbes (e.g., indole-3-acrylic acid) may attenuate atherosclerosis development in ApoE-deficient rats." (PMID 36245535, 2022). "Therefore, to understand the molecular mechanisms underlying the development of atherosclerosis, we intervened in ApoE-/- mice maintained on a high-fat diet with Nippostrongylus brasiliensis (N. brasiliensis) infection and immunized with its derived products." (PMID 36297265, 2022). "Loss of myeloid JAK2 promotes atherosclerosis in an ApoE knockout mouse model." (PMID 35169231, 2022). "Some studies suggest that being an apolipoprotein e4 (APOE e4) carrier increases the risk of atherosclerosis, and others suggest that cardiorespiratory fitness (CRF) could play a key role in atherosclerotic prevention." (PMID 36357490, 2022). "In the ApoE knockout (KO) hyperlipidemic mouse model, the loss of FoxP1 in endothelial cells promotes atherosclerosis, and endothelial FoxP1 affects the adhesion, migration, and penetration of monocytes into the vascular wall in the pathogenesis and progression of atherosclerosis." (PMID 36088337, 2022). "In addition, H19 was shown up-regulated in the blood and aortic root of atherosclerosis-prone apolipoprotein E-deficient (ApoE−/−) mice fed with western diet as compared with the control C57BL/6 mice on chow diet." (PMID 35946958, 2022). "Extracellular apoE associated with lipoproteins in plasma circulation, or derived locally in the vessel wall, as well as apoE expressed endogenously in macrophages participates in each step of this process to limit atherosclerosis progression." (PMID 36077289, 2022). "Importantly, the previous studies have shown that betaine intervention can alleviate atherosclerosis lesion in Apolipoprotein E-deficient (ApoE−/−) mice." (PMID 35277077, 2022). "For instance, it was found that upregulated JAZF1 could suppress the progression of atherosclerosis in ApoE‐deficient mice via repression of hepatic cholesterol synthesis with the involvement of CREB." (PMID 34910364, 2022). "One of the animal atherogenesis models, known as the atherosclerotic apolipoprotein E–deficient mouse, has shown severe hypercholesterolemia development on a diet with low cholesterol that contributed to increase in extensive atherosclerosis and oxidative stress." (PMID 36118710, 2022). "Mutation of ABCA1 in apoE–/– mice has little effect on atherosclerosis." (PMID 35498045, 2022). "Consistent to our findings, our previous study revealed that corylin inhibits vascular cell inflammation, proliferation, migration, and reduces atherosclerosis in ApoE-deficient mice, indicating that corylin has the potential to treat aging-associated diseases." (PMID 35264584, 2022).
atherosclerosis (continued). "ApoE deficiency (ApoE−/−) mice, fed a Western diet, are known to develop atherosclerosis easily." (PMID 35409148, 2022). "Furthermore, systemic administration of HFD-VAT-Exo enhanced atherosclerosis in hyperlipidemic ApoE-deficient mice, proposing a possible therapeutic target." (PMID 35409022, 2022). "On the other hand, CRF is a modifiable physiological attribute that may be targeted in APOE e4e4 carriers to decrease their increased atherosclerosis risk due to their genetic condition." (PMID 36357490, 2022). "Studies have demonstrated that NOX2 expression in ApoE–/– mice reduces NO bioavailability, downregulates oxidative stress, decreases ROS release, and activates vascular smooth muscle cells, which can cause atherosclerosis." (PMID 36407440, 2022). "ApoE deficiency in mice resulted in a profound susceptibility to atherosclerosis." (PMID 35845789, 2022). "Studies have shown that ApoA1 mimetic peptides may ameliorate nephropathy in a mouse model of atherosclerosis, such as ApoE-deficient mice." (PMID 35629966, 2022). "A preponderance of evidence obtained from genetically modified mice and human population studies reveals the association of apolipoprotein E (apoE) deficiency and polymorphisms with pathogenesis of numerous chronic diseases, including atherosclerosis, obesity/diabetes, and Alzheimer’s disease." (PMID 36077289, 2022). "Moreover, genetic deletion of PECAM1 in apolipoprotein E deficient (apoE–/–) mice showed a significant decrease in atherosclerosis development compared to apoE–/– controls." (PMID 35694160, 2022). "Other 64Cu-radiolabeled compounds, including [64Cu]-DOTA-DAPTA and [64Cu]-DOTA-DAPTA-comb, which has a conjugated polymeric structure, were tested in a femoral artery injury of atherosclerosis-prone apolipoprotein E-deficient (apoE−/−) mice model, showing high uptake levels in injured lesions." (PMID 35563414, 2022). "Apolipoprotein E knockout mice on a high-fat diet have been shown to be closely associated with the development of atherosclerosis, which is characterized by excessive accumulation of TC and LDL-C in the vessel wall and is considered ideal for an animal model for atherosclerosis research." (PMID 35205118, 2022). "However, despite its attractiveness and considerable circumstantial clinical evidence, our data argue against a previously unrecognized direct causal or aggravating role of Nox5 in diet-related or ApoE−/− induced atherosclerosis." (PMID 35798762, 2022). "To validate that increasing soluble ACE2 alone could also modulate diabetes-associated atherosclerosis, we treated diabetic ApoE KO mice with rmACE2 (1 mg/kg/alternate day IP) for 6 weeks." (PMID 35624851, 2022). "Previous studies have shown that inulin can reduce atherosclerosis in ApoE deficient mice." (PMID 36219347, 2022). "In contrast, deficiency of PXR decreased atherosclerosis in ApoE-deficient mice." (PMID 36119030, 2022). "As expected, ApoE deficiency induced atherosclerosis in aorta as reflected by Oil Red O staining." (PMID 35669479, 2022). "In this study, apolipoprotein E-deficient (ApoE–/–) mice were fed a high-fat diet to induce atherosclerosis, followed by the treatment with exogenous recombinant IL-17A or the neutralizing antibody to confirm the impact of IL-17A on the established atherosclerotic plaques." (PMID 36133421, 2022). "Therefore, the acceleration of atherosclerosis in the ApoE−/− SDC4−/− mice was associated with the trigger of chronic inflammation." (PMID 35842658, 2022). "Indeed, in ApoE−/− mice eNOS deficiency reduces superoxide production, indicating that eNOS uncoupling occurs during atherosclerosis." (PMID 36497101, 2022).
atherosclerosis (continued). "To determine whether TXNDC5 causatively drives atherosclerosis in vivo, we then engineered a new mouse line [Txndc5−/−::ApoE−/− (DKO)] in which Txndc5 is globally deleted in the background of ApoE−/− mice." (PMID 35061532, 2022). "Importantly, atherosclerosis was exacerbated in ApoE−/− mice carrying the RIPK1S25D/S25D mutation as compared to ApoE−/− RIPK1+/+ controls." (PMID 35625752, 2022). "Initial research suggested that primary cilia may play a role in producing atherosclerosis, as apolipoprotein-E-deficient (Apoe−/−) mice display increased primary cilia as well as increased atherosclerosis at these risk points." (PMID 35326411, 2022). "Indeed, Spirulysat® supplementation of apolipoprotein E-deficient mice, a model of a human atherosclerosis, during gestation and lactation, decrease atherosclerosis development in adult offspring." (PMID 35877734, 2022). "Further studies on the physiological role of ApoE in body iron homeostasis may be able to provide key insights into understanding whether iron can initiate atherosclerosis in ApoE deficient mice." (PMID 35669479, 2022). "In an animal experiment, cytokine therapy with IL-2/anti-IL-2 monoclonal antibody complexes could attenuate the development and progression of atherosclerosis by increasing CD4+CD25+Foxp3+ regulatory T cells in apolipoprotein E-deficient mice." (PMID 36299596, 2022). "Similar beneficial effects were observed upon pharmacologic treatment with Myriocin in the hyperlipidemic and atherosclerosis-prone apolipoprotein E (ApoE)-deficient mouse model, which prevented the development of atherosclerotic plaques and enabled the regression of established lesions." (PMID 35789435, 2022). "The clonal expansion of particular B1 cells may be relevant to other diseases: aged apoE-deficient mice with established atherosclerosis are known to harbor expansion of B1 cells with the CDR-H3 sequence AGDYDGYWYFDV." (PMID 35526067, 2022). "Interestingly, lesions from older apoE-deficient animals with advanced atherosclerosis were more similar to human plaques, which were, unsurprisingly, extremely heterogeneous." (PMID 34928417, 2022). "For this reason, it may be questioned whether the apoE–/– mouse model is an appropriate one for studying the NO/G6PD deficiency impact on atherosclerosis since the APOE locus itself modulate NO levels." (PMID 34007401, 2021). "The expression of APOE is associated with the pathology of atherosclerosis and ischemic stroke." (PMID 34702323, 2021). "Given that endothelial dysfunction increases the likelihood of atherosclerosis development, we have investigated the relationship between Nox2 and atherosclerosis development using apolipoprotein E-deficient ESMIRO mice (ESMIRO/ApoE−/−) with genetic and pharmacological inhibition of Nox2." (PMID 34571964, 2021). "Visceral fat from HFD-fed mice could release exosomes to induce the formation of macrophage foam cells by impairing their cholesterol efflux, thereby exacerbating atherosclerosis in hyperlipidemic apolipoprotein E-deficient mice." (PMID 34108967, 2021). "Notably, due to the investigation of other end points, atherosclerosis-prone apolipoprotein E-deficient (ApoE−/−) mice were utilised in this study." (PMID 33952248, 2021). "ApoE deficient (apoE-/-) mice can spontaneously develop atherosclerosis which stimulate atherosclerotic pathological processes in the arteries of humans with lesions that can be observed during the development of atherosclerosis." (PMID 33816331, 2021). "Multiple studies described the role of DKK3 in atherosclerosis development using atherosclerosis-prone apolipoprotein E-deficient (ApoE−/−) mice, but these studies showed opposing results, either suggesting accelerated or reduced atherosclerosis in DKK3−/− mice." (PMID 33883651, 2021).
atherosclerosis (continued). "Since diacylglycerol has been shown to reduce atherosclerosis in an APOE-deficient mouse model, the increase in diacylglycerol in the ε4 genotype could be a compensatory mechanism to combat rising levels of atherosclerosis." (PMID 35265943, 2021). "In addition, irisin treatment (0.5 μg/g body weight/day) inhibits the formation of carotid neointima, alleviates aortic inflammation and apoptosis and significantly reduces atherosclerosis in ApoE-deficient mice fed with high cholesterol diet." (PMID 33597894, 2021). "One study showed that overexpression of lncRNA NEXN-AS1 suppressed the NF-kB pathway, which led to decreased endothelial cell activation and monocyte recruitment in human vascular endothelial cells (HVEC), thus mitigating atherosclerosis in apoE−/− deficient mice." (PMID 33922114, 2021). "Taken together, a concurrent consumption of AceK exacerbated HCD-induced dyslipidemia and atherosclerotic lesion in ApoE−/− mice, and AceK might increase the risk of atherosclerosis under HCD." (PMID 34836239, 2021). "CD4+ T and CD8+ T cells were associated with increased atherosclerosis in ApoE−/− mice." (PMID 33841393, 2021). "Next, the effect of CD200 deficiency was studied in atherosclerosis-prone ApoE−/− mice." (PMID 33975450, 2021). "Indeed, a combination therapy with anti‐CD3 antibody and IL‐2/anti‐IL‐2 monoclonal antibody complex aimed at increasing the ratio of Tregs to pathogenic effector T cells inhibited atherosclerosis in the ApoE−/− model system." (PMID 34569651, 2021). "Accordingly, atherosclerosis-prone animals deficient for TNFα (double ApoE/TNFα KO) express lower amounts of lipoprotein scavenger receptors and show less fatty streak formation, as compared to ApoE KO littermates when 6 months of age." (PMID 33770265, 2021). "Furthermore, immune-mediated atherosclerosis was reported to be directly caused by a deficiency of the MALAT1 lncRNA in apolipoprotein E (ApoE)-/- mice." (PMID 34638541, 2021). "apoE-ε2 has both increased and decreased risk for atherosclerosis." (PMID 34746320, 2021). "Saroj Mohanta’s from Institute for Cardiovascular Prevention, Ludwig-Maximilians-University presentation centered on his discovery of a neural atherosclerosis-brain-circuit (ABC) that connects atherosclerotic arteries with the CNS in atherosclerosis-prone ApoE deficient mice." (PMID 34024277, 2021). "Indeed, increasing the expression of the apoA-1 gene in ApoE-deficient mice markedly suppressed atherosclerosis." (PMID 34202121, 2021). "Global genetic deletion of Nox1 in ApoE KO deficient diabetic mice showed decreased macrophage infiltration and reduced plaque lesion size at the aortic valve through reduction in ROS formation, suggesting the pathological relevance of Nox1 in atherosclerosis." (PMID 34829831, 2021). "However, the residual function of the “mutated ApoE” is capable of improving the lipid profiles and playing the protective role against atherosclerosis." (PMID 33663537, 2021). "Indeed, overexpression of ACE2 attenuated atherosclerosis and enhanced atherosclerotic plaque stability in a rabbit model of atherogenesis, and contrarily, its genetic deficiency worsened atherosclerosis in apoE-knockout mice." (PMID 34070749, 2021). "ApoE-deficient mice are the gold-standard model for the investigation of atherosclerosis." (PMID 34572399, 2021). "hEp not only reduces plasma cholesterol levels but also reduces the progression of atherosclerosis in aged female apoE-deficient mice with existing aortic lesions, suggesting that hEp may be a promising anti-atherosclerotic therapy." (PMID 34441867, 2021). "The contribution of TLR4 to the progression of atherosclerosis is supported by two studies showing that TLR4-deficient ApoE−/− mice have lower aortic lipid accumulation (70–80% reduction) and reduced levels of aortic atherosclerosis compared to the control mice." (PMID 35083304, 2021).
atherosclerosis (continued). "A recent multicolored VSMC lineage-tracing study in apoE-deficient mice showed that in the early stages of atherosclerosis, the fibrous cap consists in average of 70% of VSMC-derived cells and that a small but significant percentage (7%) of VSMC-derived cells expressed the macrophage marker mac3." (PMID 34572399, 2021). "In addition, ESMIRO/ApoE−/−/Nox2−/y mice had increased thoraco-abdominal aortic lipid deposition, and multiple foci of atherosclerosis associated elastin fragmentation in the aortic sinus." (PMID 34571964, 2021). "Atherosclerosis risk and hypercholesterolemia are linked by mechanisms that involve APOE." (PMID 33841127, 2021). "Moreover, B-2 depletion as a result of BAFFR deficiency in ApoE-/- mice reduced atherosclerosis progression." (PMID 34675924, 2021). "Indeed, both of these cell types are present within small areas of calcification in the innominate arteries in the advanced atherosclerotic lesions of atherosclerosis-prone apolipoprotein E-deficient (ApoE−/−) mice." (PMID 33816463, 2021). "In the present study, we generated a new mouse model of sterol-resistant SCAP (D443N mutation) in VSMCs crossed with the hyperlipidemic ApoE-/- mouse to elucidate the mechanisms linking cholesterol metabolism and inflammatory disorders in the development of atherosclerosis." (PMID 34094640, 2021). "Atherosclerosis-prone apolipoprotein E-deficient (Apoe−/−) mice are a popular model for the study of atherosclerosis as they have a reduced lipoprotein clearance and accumulation of cholesterol ester-enriched particles in the blood promoting the development of atherosclerotic plaques." (PMID 34359859, 2021). "Nevertheless, bone marrow cells expressing human apoE2 and apoE4 are similar to apoE-deficient cells in their ineffectiveness to suppress atherosclerosis in Western diet–fed ApoE−/− mice, whereas bone marrow cells expressing human apoE3 were atheroprotective when transplanted into ApoE−/− mice." (PMID 34425108, 2021). "First, we measured the arterial level of LacCer by MS and pulse-wave velocity (PWV, a measure of AS determined by high-resolution Doppler spectrum analyzer) in a mouse model of atherosclerosis (Apolipoprotein E deficient, ApoE−/− mice) fed a high fat and high cholesterol diet." (PMID 33673027, 2021). "Studies in an apolipoprotein-E-deficient (ApoE–/–) murine model of progressive atherosclerosis and abdominal aorticaneurysm showed improved visualization of vessel walls during diseaseprogression that correlated with the levels of tropoelastin as detectedby ex vivo histology and Western blotting." (PMID 34661390, 2021). "Moreover, the effect of APβG on atherosclerosis induced by HFD intake was also confirmed in apolipoprotein E-deficient mice, which is a common animal model of atherosclerosis." (PMID 33467004, 2021). "Here, we aimed to investigate the causality between CKD-AD and increased CVD risk by administering CKD fecal material to atherosclerosis-prone apolipoprotein E–knockout (ApoE–/–) mice to determine if this would result in worsened coronary atherosclerotic lesions." (PMID 33914709, 2021). "Apolipoprotein E deficient (apoE−/−) mice have been widely used as an animal model to study the pathophysiology of atherosclerosis due to the striking similarities with humans on the molecular mechanisms that lead to endothelial dysfunction and vascular plaque formation." (PMID 33557105, 2021).